ARG1 (arginase 1)
Diseases named in the same sentence as ARG1 in open-access papers (continued):
Sharing a sentence is not in itself a finding about the gene and the disease.
tumor (continued). "Several studies have uncovered that in NHL, including B cell NHL, diffuse large B cell lymphoma and NK/T cell NHL, increased expression of ARG1, IDO and iNOS in MDSCs is relevant to the enhancement of tumor growth and suppression of T cells." (PMID 32325683, 2020). "Next, we determined the relative expression levels of ARG1/NOS2 in those circulating and tumor-infiltrating MDSCs by qRT-PCR and Western blotting." (PMID 32415175, 2020). "A recent study demonstrated that murine tumor cells cultured under ER stress conditions produced lactic acid, a by-product of aerobic glycolysis, which induced the transcription of VEGF and arginase 1 in recipient macrophages." (PMID 33117793, 2020). "Previous studies have shown that there is a large amount of ARG1 and NOS2 in MDSCs under tumor conditions and that these factors can inhibit the function of T cells, thereby creating an important mechanism for immune-avoidance." (PMID 32415175, 2020). "ROS, ARG1, iNOS PGE2, and TGF-β have recently been suggested to exert suppressive effects on B-cell proliferation and antibody production by tumor-induced MDSCs." (PMID 32793192, 2020). "On the one hand, MDSCs can produce high levels of immunosuppressive molecules, such as arginase 1 (ARG1), iNOS, TGFβ, IL-10, COX2, and indoleamine 2,3-dioxygenase (IDO), to immediately inhibit effector T cell-mediated cytotoxicity to tumor cells." (PMID 32551121, 2020). "Tumor-infiltrating macrophages have been classified as M1 (antitumor) or M2 (protumor) according to the co-expression of CD68, iNOS or MRC1/CD206, CD163, Arg1, and other markers in in vitro models." (PMID 32168749, 2020). "MDSCs can promote the survival and angiogenesis of tumor cells and inhibit the function of T cells by producing the immunosuppressive molecules TGF-β, IL-10, Arg1, and iNOS." (PMID 32823603, 2020). "First, TAMs highly express Arg1, VEGF, osteopontin, MMPs, IL-10, TGFβ, and TNFα and thus inhibit the anti-tumor immune response." (PMID 32518979, 2020). "Within the tumor, expression of immunosuppressive molecules, including Cd274 (PDL1) and Arg1, increased at later time points." (PMID 32433953, 2020). "Lastly, after the purified tumour-infiltrating PMN-MDSCs were cultured for 24 h in vitro, cells from the HSD group expressed more TNF-α and ICAM-1 and less prostaglandin E2 (PGE2), Arg1, CCL2 and CCL5 than those from the NSD group." (PMID 32265505, 2020). "In parallel, elevated levels of Cd74 and Arg1 RNA in tumor microglia was also detected at the protein expression level of CD74 and ARG1 protein." (PMID 32299465, 2020). "The pattern of expression of cellular markers (CD11b, MERTK, F4/80, Arginase-1 and CD206) is consistent with the generation of M2 macrophages in response to tumor cell-derived exosomes." (PMID 32456301, 2020). "In contrast, M2 macrophages express immunosuppressive cytokines and growth factors like IL-10, Arg-1, CD206, VEGF, and EGF, and can thereby promote tumor proliferation, metastasis, and angiogenesis." (PMID 32850356, 2020). "For example, tumor-infiltrating MDSCs stimulated with TGF-β and IL-10 demonstrated high ARG1 activity." (PMID 32499785, 2020). "Noteworthy are in particular two markers (ARG1 and IDO1) that cooperate to establish an immunosuppressive tumor microenvironment." (PMID 31960110, 2020). "Recently, it is shown that tumor-infiltrating MDSCs have increased fatty acid oxidation (FAO), which is accompanied by upregulated ARG1, increased NO, and PNT production, and that FAO inhibition impairs the suppressive activity of MDSCs in vitro and in vivo." (PMID 32793192, 2020). "Accordingly, entinostat, a class I HDAC inhibitor, in combination with anti-PD-1 antibodies, reduces the expression of ARG1, iNOS, and COX2 in MDSCs, finally inhibiting their immunosuppressive capacity and delaying tumor growth in mice." (PMID 32823961, 2020).
tumor (continued). "Arginase-1 levels were comparably low in splenic PMN- and M-MDSC during tumor development, but highly upregulated in tumor-resident MDSC." (PMID 31694706, 2019). "M2 macrophages express anti-inflammatory mediators; promote angiogenesis mediators, such as arginase-1 (ARG1), IL-10, TGF-β1, and VEGF; and play a pivotal role in tissue repair, reconstruction and tumours." (PMID 31182110, 2019). "By secreting cytokines such as IL-6, IL-18, TNF-α, TNF-β, IL-1β, IFN-γ and IL-23, arginase 1 (ARG1) and ECM-modifying enzymes into the TME, TAMs contribute to tumor cell growth, angiogenesis, invasion and metastasis." (PMID 30781344, 2019). "In SK-MES-1 and SW900 xenograft models, PEGylated ARG1 (BCT-100, 60 mg/kg) downregulated the intratumoral arginine level and suppressed tumor growth via apoptosis or concurrently with G1 arrest." (PMID 30808864, 2019). "IHF results showing F4/80+ macrophages expressed M2-type macrophage markers like arginase 1 (Arg1) and CD163 also confirmed that M2 but not M1-macrophages predominated in the EndoMT cells-promoted tumor masses." (PMID 31847880, 2019). "Mice were inoculated i.p. with control (ID8-pLVX) or ARG1-transduced (ID8-ARG1) tumor cells and were treated with OAT-1746 or PBS starting from day 15 after inoculation of tumor cells." (PMID 31278254, 2019). "Myeloperoxidase is another ROS-producing enzyme that, along with ARG-1, is more abundantly expressed by PMN-MDSCs than neutrophils, contributing to suppression of antigen-specific T cell responses in tumor bearers." (PMID 31130949, 2019). "To verify the inhibitory effect of POG on arginine metabolism in B16-F10 tumour-bearing PMN-MDSCs, we used qRT-PCR and Western blot analysis to examine the effect of POG on the expression of iNOS and Arg-1 in PMN-MDSCs." (PMID 31462297, 2019). "At this respect, enhanced expression of arginase 1 (ARG1) and indoleamine 2,3-dioxygenase 1 (IDO1), enzymes that catalyze the degradation of arginine and tryptophan, respectively, have been documented in tumor infiltrating DCs and MDSCs." (PMID 31535086, 2019). "We surveyed ARG1 expression in panel of twelve human cancer cell lines from originating from different tissues to first determine whether cancer cells are dependent on arginase activity in vitro and then to determine whether tumor cell arginase expression correlates with sensitivity to Cpd9." (PMID 30728077, 2019). "Arginase-1 inhibitor, CB-1158, combined with PD-L1 or CTLA-4 blockade also synergized the tumor suppressive effect on primary tumors and metastases and markedly prolonged the survival, even though low efficacy was observed with monotherapy." (PMID 31174610, 2019). "We think that targeting ARG1, with the new upcoming generation of engineered MDSC-specific nanoparticles, will be of great interest for many cancer types to unleash anti-tumor immunity." (PMID 31533831, 2019). "Levels of ARG1 and NOX2 were reduced by oxaliplatin treatment, resulting in the neutralization of the immunosuppression and tumor‐promoting activity of MDSCs." (PMID 30592157, 2019). "Strong staining for ARG1, with ARG scores up to 280 (see “Methods” section for the ARG score definition) was observed in 9 patients (10.71% of the tumor samples)." (PMID 31278254, 2019). "These N2-like neutrophils favour tumor progression and metastasis through the release of VEGF to promote angiogenesis, and the expression of arginase 1 to suppress cytotoxic T cell anti-tumoral activity." (PMID 30917934, 2019). "We next examined the expression of Arg-1 and TGF-β1, classical markers of the M2 phenotype of macrophages, and observed their elevated levels in gemcitabine-treated tumor tissues." (PMID 30097594, 2018). "TAMs in the irradiated tumour microenvironment express higher levels of M2 markers (Arg-1, COX-2), and promote early tumour growth in vivo." (PMID 30178305, 2018).
tumor (continued). "Arginase 1 is a critical immunosuppressive molecule that can directly inhibit CD8 T-cell function and stimulate TAMs to promote tumor growth." (PMID 30619286, 2018). "Arginase 1 (Arg1), depending on STAT3 signaling, and inducible nitric oxide synthase (iNOS) in MDSC are capable of depleting L-arginine from the tumor microenvironment, such that T cells are unable to multiply." (PMID 30060755, 2018). "In cancer progression, MDSCs inhibit the anti-tumor immune responses induced by CD4+ T cells, CD8+ T cells and NK cells by releasing Arg1, ROS and iNOS." (PMID 29914443, 2018). "Experimental models have shown that tumor cells can induce HIF-1 in macrophages, upregulating VEGF, and Arginase 1 (ARG1) expression via lactate synthesis and generating a molecular signature found in alternatively activated macrophages." (PMID 29584702, 2018). "The production of lactate has been shown to contribute to the tumor microenviroment and was sufficient to induce VEGF and Arg1 expression via HIF1alpha to promote angiogenesis and macrophage polarization." (PMID 28558019, 2017). "In this study, we have demonstrated for the first time that tumor-shed gangliosides, especially monosialoganglioside GM1, greatly increased the expression of Arg-1, a prominent marker of M2 polarization in macrophages." (PMID 28032600, 2017). "Macrophages from irradiated tumors show increased expression of arginase 1 (Arg1), COX2, and iNOS that promote tumor growth." (PMID 28603525, 2017). "PMN-MDSCs, the major source of arginase 1 in tumor-bearing hosts, reduce extracellular arginine by arginine incorporation via CAT-2B or arginase 1 production." (PMID 28223985, 2017). "We observed significantly higher expressions of IL-33, arginase 1, IL-10 and FoxP3 in NSCLC tumor tissues than adjacent tissues." (PMID 28978138, 2017). "One important illustration of this is the striking resemblance that human tumor-resident myeloid-derived suppressor cells (MDSCs) have with human peripheral blood neutrophils; both cell subsets are CD33+CD11b+HLA-DR− and arginase-1+ (Arg-1)." (PMID 28220123, 2017). "We also stained the tissue for human arginase-1 that is transcriptionally upregulated with STAT3, and we found dramatic reduction of this immunosuppressive enzyme in the STAT3 suppressed tumor." (PMID 28008146, 2017). "By inhibiting MDSC-dependent nitric oxide and arginase-1, PDE5 inhibitors have been shown to increase tumour infiltration by cytotoxic T-cells and improve the anti-tumour efficacy of adoptive T cell therapy in relevant mouse models." (PMID 29208938, 2017). "Further study indicated that QRHX inhibited cancer-related inflammation in tumor by decreasing infiltration of TAMs and IL-6 and TNF-α production and meanwhile decreased arginase 1 (Arg-1) expression and increased inducible NO synthase (iNOS) expression." (PMID 28630636, 2017). "IL-33 neutralization significantly inhibited the expressions of M2 TAM-related genes including arginase 1, IL-10 and VEGF in tumor tissues." (PMID 28978138, 2017). "This suggests that some tumour-derived and secreted molecules can mediate VEGF and ARG1 expression in macrophages through a mechanism involving HIF1α stabilization under normoxic conditions." (PMID 27083002, 2016). "Both tumor-infiltrating CD33+CD11b+HLA-DR−/lowCD14+ and CD33+CD11b+HLA-DR−/lowCD15+ cells expressed ARG1." (PMID 28008330, 2016). "Interestingly, the hypoxia-inducible factors (HIF)-1α and HIF-2α are expressed differentially in M1- and M2-polarized macrophages and regulate inducible NOS-2 (M1) and Arg-1 (M2), respectively, suggesting that tumor hypoxia may mediate the transition of M1 to M2." (PMID 27191744, 2016). "Tumour conditioned medium shows the same capacity to induce VEGF and ARG1 expression in an HIF1α dependent manner, as indicated by the fact that their expression is prevented in an HIF1α null background." (PMID 27083002, 2016).
tumor (continued). "PGE2 has been found to promote MDSCs recruitment to the tumor microenvironment through the induction of CXCL12 chemokine and lead to an upregulation of ARG1 expression, which accordingly regulates MDSCs-related T-cell immune suppression." (PMID 27032536, 2016). "Real-time RT-PCR analysis of the transcript levels of iNOS and ARG-1 showed that L-Arg treatment significantly elevated the expression of iNOS (P < 0.05, t-test), compared with PBS and L-Arg + AG groups in tumor." (PMID 27246354, 2016). "Despite exhibiting a mature phenotype, arginase-1-expressing TIDC, described in the NeuT mammary murine tumor model, can suppress T lymphocyte proliferation by depleting arginine from the environment." (PMID 26491691, 2015). "Our findings show that tasquinimod changes the polarization of macrophages in the tumor by several different parameters, such as an increase in MHC class II, CD86 and Nos2 expression and a reduced arginase-1 and CD206 expression." (PMID 26673090, 2015). "IMCs in our model also secrete M2 marker proteins including YM1, arginase-1, MRC1 (soluble CD206) and legumain and promote tumour cell growth in vitro and ex vivo (Fig3)." (PMID 26183450, 2015). "The results indicate that high level of CD14, ARG1, and FOXP3 mRNA expression in primary NB tumor significantly correlated to a better survival." (PMID 26161395, 2015). "The production of polyamines via Arginase 1 can stimulate tumor growth, and TAMs from RETAAD tumors expressed high levels of Arg1." (PMID 25294815, 2014). "Both Arg1 protein and enzyme activity was higher in CML PMNs than Gr-MDSCs, demonstrating, for the first time, a critical role of CML PMNs on the tumor microenvironment with a potential immunosuppressive activity." (PMID 25014230, 2014). "The percent of Gr1+CD11b+ MDSCs expressing iNOS and Arg-1 were significantly higher in KCM as compared to KCKO and 3T12-tumor-bearing mice." (PMID 24605110, 2014). "M2-like TAM have high levels of mannose receptor-1 (MRC1/CD206), arginase-1 (Arg1), IL-10 and chemokines CCL22 and CCL17, whereas anti-tumor M1-like TAM express high interferon (IFN)γ and IL-1α/β levels; TNFα marks both M1- and M2-polarized TAM." (PMID 24317954, 2013). "In addition to the nutritional demands of the tumor, an important starting point of this study was the expected depletion of L-arginine through immune cells, based on the increase in myeloid cells over-expressing the enzyme arginase 1 in the same patient cohort." (PMID 24237611, 2013). "The results showed that MDSCs from IL-17−/− tumor-bearing mice expressed lower levels of Arg-1, MMP9, and S100A8 than those from wild-type tumor-bearing mice." (PMID 24453427, 2013). "M2-type macrophages from experimental tumors and various types of cancers express arginase-1 (Arg1), IL-10 and transforming growth factor beta 1 (TGF-β1), support tumor invasion, angiogenesis and matrix remodelling." (PMID 21901144, 2011). "Collectively, these results suggest that ARG1 and ARG2 expressed by LNCaP cells are enzymatically active and participate in important physiological processes such as cellular proliferation and tumor-derived immunosuppression." (PMID 20711410, 2010). "Clinical samples demonstrate that peripheral blood Arg1+neutrophils increase with advancing tumour stages and exhibit a negative correlation with CD8+T cell proportions." (PMID 41491612, 2026). "Hypoxia enhances glycolytic flux by upregulating GLUT1/LDHA, and intracellular lactate accumulation triggers p300-induced histone H3K18 lactylation modification, directly regulating arginase-1 (ARG1) expression to suppress CD8+/CD4+ T cell activity and promote tumor immune escape." (PMID 41181157, 2025). "The expression of ARG1 in MDSCs was significantly elevated in tumor‐bearing mice treated with 25HC compared to the no‐treatment group." (PMID 41020041, 2025).
tumor (continued). "Tumor-derived lactate, absorbed by macrophages through monocarboxylate transporters (MCT1–4), activates HIF-1α, which subsequently upregulates the expression of vascular endothelial growth factor (VEGF) and arginase-1 (Arg1)." (PMID 40433363, 2025). "However, both groups exhibited a slight increase in M2-like phenotype markers within tumor samples, with higher expression of the M2 markers CD206 and Arg1." (PMID 40634306, 2025). "Supplementing arginine or inhibiting the activity of ARG-1 and INOS could represent promising strategies to augment anti-tumor immune responses but their clinical implementation remains a significant challenge." (PMID 39925801, 2025). "They inhibit anti-tumor immunity through multiple mechanisms, including the depletion of L-arginine in the TME via inducible nitric oxide synthase (iNOS) and arginase-1 (Arg-1), and the exhaustion of tryptophan through indoleamine 2,3-dioxygenase (IDO), which directly suppresses T cell activation." (PMID 41368628, 2025). "Immunohistochemistry showed focal HepPar1 positivity in tumor cells; Arginase-1 and CK7 were negative." (PMID 40426891, 2025). "Moreover, Kla remodels immune cell functions (e.g., by activating genes like Arg1/PD-L1 and pathways like TGF-β), inhibiting NKT cell activity to facilitate tumor immune evasion." (PMID 41181157, 2025). "Furthermore, lactate produced by tumor cells has been shown to enhance the expression of genes such as VEGFA and Arg1 via HIF-1α, thereby promoting M2 macrophage polarization." (PMID 40129528, 2025). "M2-type macrophages exert synergistic effects in reducing inflammatory responses, promoting tissue repair, enhancing immune suppression, and supporting tumor growth by secreting anti-inflammatory cytokines (IL-10 and TGF-β) and highly expressing arginase-1 (Arg1)." (PMID 40657246, 2025). "It inhibited the M2-like polarized tumor-promoting phenotype of macrophages, as evidenced by a decrease in CD206 expression and an increase in CD86 expression in flow cytometry, as well as a decrease in ARG1 protein levels in Western blot assays." (PMID 40430260, 2025). "Previous studies have reported that tumor-associated macrophages (TAMs) primarily secrete anti-inflammatory cytokines such as ARG-1, IL-10, and TGF-β to generate an anti-inflammatory response, participate in tumor angiogenesis and extracellular matrix remodeling." (PMID 40463876, 2025). "It inhibited the M2-like polarized tumor-promoting phenotype of macrophages, as evidenced by a decrease in CD206 expression and an increase in CD86 expression in flow cytometry, as well as a decrease in ARG1 protein level in Western blot assays." (PMID 40430260, 2025). "M2 macrophages release immunosuppressive cytokines, including vascular endothelial growth factor (VEGF), arginase-1 (Arg-1), transforming growth factor-β (TGF-β) and IL-10, thereby contributing to tumor progression by facilitating angiogenesis, invasion, and migration." (PMID 40352926, 2025). "Indeed, overexpression of miR155 induced repolarization of M2-activated macrophages into pro-inflammatory M1-like macrophages and also reduced tumor progression of esophageal cancer via downregulation of FGF2, IL-10, Arginase-1 and IL-22." (PMID 40050933, 2025). "Consequently, ARG1 inhibition enhances the effects of immunotherapy, increases tumor-infiltrating CD8+ T cell and natural killer (NK) cell populations and reduces tumor growth in mice." (PMID 39863828, 2025). "The qPCR detection of showed that ARG1 and transforming growth factor‐β (TGF‐β) were significantly increased in migrated neutrophils attracted by culture medium of tumor cell overexpressing DTX2, which indicated the pro‐tumoral characteristic of these migrated neutrophils." (PMID 39733452, 2025). "In our patient, tumor cells stained positive for HepPar-1, Arginase-1, and Glypican-3, but negative for CK7/CK19, excluding CCA." (PMID 40997628, 2025).